GPX5 (glutathione peroxidase 5)
Description:
Protects cells and enzymes from oxidative damage, by catalyzing the reduction of hydrogen peroxide, lipid peroxides and organic hydroperoxide, by glutathione. May constitute a glutathione peroxidase-like protective system against peroxide damage in sperm membrane lipids.
Synonyms: EGLP; GPx-5; GSHPx-5; HEL-S-75p
Tractability: Antibody: its Gene Ontology location is reachable by antibodies, with high confidence; UniProt places it where antibodies can reach, with medium confidence; UniProt predicts a signal peptide or a membrane-spanning region.
Gene: Protein-coding gene on chromosome 6 (28,525,881 to 28,534,955, forward strand). Ensembl gene ENSG00000224586.
Subcellular location: Secreted
Pathways (Reactome):
Cellular responses to stimuli: Detoxification of Reactive Oxygen Species
Gene Ontology:
Molecular function: glutathione peroxidase activity; peroxidase activity
Biological process: cellular response to oxidative stress; lipid metabolic process; cellular oxidant detoxification; response to oxidative stress
Cellular component: extracellular region
Genetic constraint (gnomAD): Loss-of-function variants: 12 observed, 14.15 expected, observed/expected ratio (o/e) 0.85, 90% interval 0.54 to 1.37. The upper end of that interval is the gene's LOEUF score, 1.37, which puts it in group 5 of 6, group 1 being the genes least tolerant of losing a copy. Missense variants: 197 observed, 228.5 expected, observed/expected ratio (o/e) 0.86, 90% interval 0.77 to 0.97. Synonymous variants: 79 observed, 88.29 expected, observed/expected ratio (o/e) 0.89, 90% interval 0.75 to 1.08.
Homologues: Orthologues: macaque GPX5 (98% identical), chimpanzee GPX5 (95% identical), dog GPX5 (77% identical), rabbit GPX5 (75% identical), pig GPX5 (70% identical), zebrafish gpx3 (49% identical), tropical clawed frog gpx3 (40% identical), zebrafish gpx1a (40% identical), Caenorhabditis elegans gpx-3 (36% identical), Caenorhabditis elegans gpx-5 (35% identical), zebrafish gpx1b (33% identical), Drosophila melanogaster Gpxl (28% identical), and 4 more. Paralogues in human: GPX3 (69% identical), GPX6 (67% identical), GPX1 (42% identical), GPX2 (39% identical), GPX8 (28% identical), GPX7 (27% identical), GPX4 (25% identical).
Diseases named in the same sentence as GPX5 in open-access papers:
GPX5 is named in the same sentence as 17 diseases in open-access papers, as found by Europe PMC text mining. Sharing a sentence is not in itself a finding about the gene and the disease. The quoted sentences say what the papers report.
breast carcinoma (3 papers, 2020). "As studies of the functions of GPx5, GPx6 and GPx7 in the development of breast cancer are limited, it is difficult to determine their underlying mechanisms." (PMID 32571353, 2020). "Breast cancer patients with higher expression of GPX2, GPX3 or GPX5 had better prognosis." (PMID 32782436, 2020). "However, the other four GPXs family genes (GPX1, GPX5, GPX6 and GPX7) showed no statistical diagnostic values in breast cancer." (PMID 32782436, 2020).
infertile (2 papers, 2016 to 2021). "In mice, a GPX5-KO model demonstrated that the lack of GPX5 was associated with infertility, specifically with embryo-fetal defects, miscarriages and perinatal mortality." (PMID 27627110, 2016). "Similarly, a conserved decrease in CRES expression has been reported in infertile mouse models generated by either ablation of the c-ros tyrosine kinase receptor or the transgenic expression of the glutathione peroxidase 5 gene (GPX5) in all the epididymal segments." (PMID 33937261, 2021).
Obesity (2 papers, 2020 to 2023). Accumulation of substantial excess body fat. "We found two haplotypes associated with obesity by BMI (in GPX3 and in GPX5 and GPX6) and five haplotypes associated with obesity by PBF (in GPX3, in PON1, and in PON2 and PON3)." (PMID 32752212, 2020). "In this study we found six haplotypes associated with obesity, two of them (one in GPX3 and the other in GPX5 and GPX6) when obesity was classified by BMI." (PMID 32752212, 2020). "Six haplotypes were significantly associated with obesity; two of them (one in GPX3 and the other one in GPX5 and GPX6) showed this association in a protective direction when obesity was classified by BMI." (PMID 32752212, 2020). "The present study aimed to identify associations linking allelic variants of the PCSK1, TMEM18, GPX5, ZPR1, ZBTB16, and PPARG1 genes with anthropometric and biochemical traits and metabolic diseases (obesity or metabolic syndrome) in an adult population from northwestern Mexico." (PMID 37761915, 2023). "On the other hand, the lack of association of the other SNPs (TMEM18 rs6548238 C allele, GPX5 rs445870 G allele, ZPR1 rs964184 G allele, and ZBTB16 rs7106340 T allele) with metabolic diseases (obesity or metabolic syndrome) in this work could have been influenced by the sample size." (PMID 37761915, 2023). "We found six haplotypes associated with obesity—two of them (one in GPX3 and the other in GPX5 and GPX6) in a protective direction when obesity was classified by BMI." (PMID 32752212, 2020).
thyroid cancer (2 papers, 2015 to 2022). "As a conclusion, according to our data PC Cl3, PC PTC1, PC E1A cell model systems corresponded to human NOX2, NOX4, SOD3, CATALASE, GPX5, and GPX7 gene expressions in thyroid cancer." (PMID 26664298, 2015). "Glutathione peroxidase family showed variable gene expression: GPX1 and GPX2 expression analysis suggested minor increase in mRNA synthesis, GPX3, GPX5, and GPX7 expression was downregulated in thyroid cancers, whereas GPX4 expression did not change." (PMID 26664298, 2015).
atopic dermatitis (1 paper, 2022). "Also other biomarkers were discovered through proteomics, such as acetaldehyde dehydrogenase 1 (ALDH1) for atopic dermatitis and GPX5 for melanoma." (PMID 36338621, 2022).
brain tumors (1 paper, 2023). "In fact, we have not found changes in gpx5 expression in males with brain tumors, whereas in females with brain tumors, an important increase in the expression of this enzyme appears." (PMID 37761814, 2023).
ischemia (1 paper, 2023). A hypoperfusion of the BLOOD through an organ or tissue caused by a PATHOLOGIC CONSTRICTION or obstruction of its BLOOD VESSELS, or an absence of BLOOD CIRCULATION. "Furthermore, Il9, Gpx5, and Gpx6 were completely disconnected from the main gene cluster in the ischemia+Placebo network." (PMID 37426668, 2023).
cancer (2 papers, 2013 to 2020). A tumor composed of atypical neoplastic, often pleomorphic cells that invade other tissues. "We have also identified two antioxidant genes, GPX5 and TXNDC2, which are positively regulated by p38 MAPK signalling in cancer cells and control the basal JNK activity levels." (PMID 24115572, 2013). "This indicates that GPX5 and TXNDC2 are both good candidates to mediate the upregulation of ROS observed upon p38 MAPK inhibition in cancer cells." (PMID 24115572, 2013).
tumor (1 paper, 2023). "Conversely, the tumor tissue exhibited elevated relative expression levels in all isoforms, except for gpx4, which remained unchanged, and gpx5, which exhibited alterations solely in female animals." (PMID 37761814, 2023). "However, GPx-5 plays an important role in the maintenance of the tissue microenvironment, cellular protection against oxidative stress, and maintenance of the DNA structure integrity, which needs to be studied at the brain tissue level as a consequence of tumor development." (PMID 37761814, 2023).
GPX5 also shares sentences with these, for which no sentence is quoted: bacterial infections (1 paper); colon cancer (1); glaucoma (1); melanoma (1); metabolic disease (1); metabolic syndrome (1); rectal cancer (1); sarcoma (1).